Y_RNA (Y RNA )
Gene: Miscellaneous RNA gene on chromosome 17 (19,649,494 to 19,649,587, reverse strand). Ensembl gene ENSG00000275982.
Homologues: Orthologues: chimpanzee Y_RNA (98% identical), macaque Y_RNA (89% identical). Paralogues in human: Y_RNA (86% identical), RNY4P3 (84% identical), RNY4 (83% identical), Y_RNA (82% identical), Y_RNA (81% identical), RNY4P14 (80% identical), RNY4P6 (80% identical), RNY4P7 (80% identical), Y_RNA (80% identical), RNY4P10 (79% identical), RNY4P25 (79% identical), Y_RNA (79% identical), and 85 more.